NTRK1 (neurotrophic receptor tyrosine kinase 1)
Diseases named in the same sentence as NTRK1 in open-access papers (continued):
Sharing a sentence is not in itself a finding about the gene and the disease.
hereditary sensory and autonomic neuropathy type 4 (6 papers, 2022 to 2024). "Mutations in the NTRK1 gene cause hereditary sensory and autonomic neuropathy type IV (HSAN-IV), or congenital insensitivity to pain with anhidrosis." (PMID 36761411, 2023). "CIPA, also known as hereditary sensory and autonomic neuropathy type 4 (HSAN type 4), is caused by mutations in the NTRK1 gene on chromosome 1q23.1, spanning over 25 kb with 17 exons and 16 introns." (PMID 38581121, 2024).
uterine sarcomas (6 papers, 2020 to 2025). "In NTRK-rearranged uterine sarcomas, NTRK1 is more frequently involved in gene fusions than NTRK3, and TPM3::NTRK1 fusion is the most common translocation reported." (PMID 38151535, 2024). "In addition, RNA or DNA sequencing of 15 cases of NTRK-rearranged uterine sarcomas revealed that one case showed a fusion of C16orf72 with NTRK1." (PMID 38643468, 2024). "The clinical, morphological and immunohistochemical features of this lesion are consistent with those reported in the literature, but to the best of our knowledge, this is the first description of a novel NUMA1::NTRK1 fusion in an NTRK-rearranged uterine sarcoma or any other tumour type." (PMID 38151535, 2024). "NTRK1 rearrangements by gene fusion were previously found in a subset of cervical/uterine sarcomas, but not in LMS." (PMID 39691991, 2025).
head and neck cancer (5 papers, 2012 to 2025). A primary or metastatic malignant neoplasm affecting the head and neck. "The only fusion gene detected in head and neck cancer was ETV6::NTRK3 (n = 22); in STS, ETV6::NTRK3 (n = 7) and LMNA::NTRK1 (n = 5) were common." (PMID 38925616, 2024).
schizophrenia (5 papers, 2016 to 2024). A major psychotic disorder characterized by abnormalities in the perception or expression of reality. "In particular, the rs556840308-A (G4S) NTRK1 variant, that impairs TrkA exposure to the membrane, has been identified in patients with schizophrenia in an American population." (PMID 38646100, 2024).
squamous cell carcinoma (5 papers, 2018 to 2024). A carcinoma arising from squamous epithelial cells. "Data from studies in patients with primary lung cancer showed that NTRK1 has a high specificity (92.8%) in a group of 686 patients with squamous cell carcinoma, but has a low sensitivity 71.6%." (PMID 35860155, 2022). "NTRK1 and NTRK2 are preferentially expressed in squamous cell carcinoma as compared to other histological types, especially adenocarcinoma." (PMID 35860155, 2022). "However, another study found that the presence of NTRK1 does not significantly influence the prognosis of squamous cell carcinoma or lung adenocarcinoma, but is a positive prognostic factor for patients with squamous cell carcinoma regardless of gender, age, stage or smoking status." (PMID 35860155, 2022).
autism (4 papers, 2018 to 2022). Persistent deficits in social interaction and communication and interaction as well as a markedly restricted repertoire of activity and interest as well as repetitive patterns of behavior. "One study discovered an association of several SNPs in NTRK1 with autism behavioral traits as measured by empathy quotient and autism spectrum quotient." (PMID 31827489, 2019). "In NPCs, we continued to see evidence for disruption in NOGO signaling through increased expression of both NOGO (RTN4) and the TRKA receptor (NTRK1), which is associated with autism through rare protein-coding variation, is a known interactor with P75 and is modulated by NOGO signaling." (PMID 35760976, 2022).
hereditary sensory and autonomic neuropathy (4 papers, 2011 to 2024). An instance of sensory peripheral neuropathy that is caused by an inherited modification of the individual's genome. "NTRK1 is a tyrosine kinase and is closely involved in the diseases Hereditary Sensory and Autonomic Neuropathy (HSAN) IV and V." (PMID 21858043, 2011).
metastatic colorectal cancer (4 papers, 2009 to 2023). "Additionally, LMNA-NTRK1-positive patients with metastatic colorectal cancer showed a remarkable response to Entrectinib, followed by resistance to Entrectinib mediated by NTRK1 G595R and G667C mutations and these mutations also showed immense resistance to Larotrectinib and TSR-011." (PMID 31936239, 2020).
Spitz nevi (4 papers, 2015 to 2021). "NTRK1 fusions were found also in seven out of twenty-three (11%) Spitz nevi and in one out of four (25%) spitzoid melanomas." (PMID 34830218, 2021).
allergic asthma (3 papers, 2019 to 2022). A asthma with a basis in a pathological type I hypersensitivity reaction. "Namely, for environment IgE sensitization (METTL1), for allergic asthma (NTRK1), and several for FeNO (MAP3K14, NTRK1, FBXL7, PCSK6, SLC9A3, CDH26, CAPN14, and MAP3K14)." (PMID 31300640, 2019).
colorectal tumors (3 papers, 2016 to 2023). "For example, Lee and colleagues showed that colorectal tumors positive for TrkA expression presented NTRK1 rearrengements." (PMID 27145455, 2016). "We originally reported the identification of a chromosomal rearrangement involving NTRK1 (encoding the TRKA protein) and the TPM3 gene in the KM12 colorectal tumor cell line and showed for the first time that the resulting TPM3-TRKA fusion protein is an oncogenic driver sensitive to TRKA inhibitors." (PMID 28903424, 2017). "There were no instances of MSI in 56 non-colorectal tumors carrying ALK, ROS1, RET or NTRK1 rearrangements." (PMID 37686416, 2023).
diabetic neuropathy (3 papers, 2018 to 2025). A chronic, pathological complication associated with diabetes mellitus, where nerve damages are incurred due to diabetic microvascular injury involving small blood vessels that supply these nerves, resulting in peripheral and/or autonomic nerve dysfunction. "Crucially, our demonstration that SMIR-induced spinal NTRK1 upregulation recapitulates patterns observed in diabetic neuropathy models reveals evolutionary conservation of this pathway—a finding substantiated by human genetic studies linking NTRK1 polymorphisms to neuropathic pain susceptibility." (PMID 40722704, 2025).
Down syndrome (3 papers, 2015 to 2019). "When compared to AML controls, NTRK1 expression is significantly higher in AMKL and even higher in Down syndrome patients with AMKL (p=0.026, p=0.041)." (PMID 30046390, 2018).
metastasis (3 papers, 2021 to 2026). The spread or migration of cancer cells from one part of the body (where they first appeared) to another. "Genomic analysis revealed site-specific correlations: MYC mutations with pleural metastasis, NTRK3 with brain metastasis, ALK with adrenal metastasis, and NTRK1 with intrapulmonary metastasis." (PMID 42187573, 2026).
metastatic cancer (3 papers, 2004 to 2023). A carcinoma which has spread from the original site of growth to another anatomic site. "NTRK1-3 amplifications are associated with metastatic cancer." (PMID 35008821, 2021). "The studies evaluated both the safety and efficacy of orally administering entrectinib to adults with locally advanced metastatic cancer with NTRK1, NTRK2, NTRK3, ROS1, or ALK rearrangements." (PMID 37111737, 2023). "The ALKA-372-001, STARTRK-1, and STARTRK-2 studies evaluated both the safety and efficacy of orally administering entrectinib to adult patients with locally advanced metastatic cancer with NTRK1, NTRK2, NTRK3, ROS1, or ALK rearrangements." (PMID 37111737, 2023).
rhabdomyosarcoma (3 papers, 2018 to 2025). A rare aggressive malignant mesenchymal neoplasm arising from skeletal muscle. "Finally, a mutation of NTRK1 was identified in a sample of alveolar rhabdomyosarcoma." (PMID 29541442, 2018).
spindle cell sarcoma (3 papers, 2024 to 2025). A malignant mesenchymal neoplasm composed of spindle-shaped cells. "In summary, we report a case with a novel NUMA1::NTRK1 fusion in an NTRK-rearranged spindle cell sarcoma of the uterine cervix." (PMID 38151535, 2024).
thymoma (3 papers, 2014 to 2023). A neoplasm arising from the epithelial cells of the thymus. "Amplification in the NTRK1 gene was found in a patient with thymoma." (PMID 37474689, 2023). "A potentially targetable amplification in the NTRK1 gene was found in an unresectable, stage III, type B3 thymoma." (PMID 35749302, 2022). "Amplification in the NTRK1 gene was found in an unresectable, stage III, type B3 thymoma." (PMID 35749302, 2022).
uveal melanoma (3 papers, 2024 to 2025). A melanoma derived from melanocytes of the uveal tract. "Increased NTRK1 expression was a risk factor for uveal melanoma (UVM), and high NTRK2 and NTRK3 expression was associated deceased OS, DSS, and PFI in bladder urothelial carcinoma (BLCA)." (PMID 38357305, 2024).
craniosynostosis (2 papers, 2018 to 2025). Craniosynostosis is defined as the premature fusion of one or more cranial sutures leading to secondary distortion of skull shape resulting in skull deformities with a variable presentation. "Out of seven genes with a high (< 10%) or moderate (< 25%) HI score (NES, CCT3, MEF2D, LAMTOR2, ETV3, SSR2, NTRK1), none of them have been linked to craniosynostosis." (PMID 29845577, 2018).
esophagogastric adenocarcinoma (2 papers, 2021 to 2025). "Outlier expression of the targetable oncogene MET was detected in a patient with GEJ adenocarcinoma and of NTRK1 in a patient with medullary colon cancer, respectively." (PMID 34385467, 2021). "Three cases (0.08%, n = 3/3960) expressing NTRK1 fusions (RRP15-NTRK1, NAV1-NTRK1, and one case with both PEAR1-NTRK1 and NTRK1-STK11 fusions) were detected in esophagogastric adenocarcinoma (esophageal, esophagogastric, or gastroesophageal junction)." (PMID 41516212, 2025).
gastric tumor (2 papers, 2023). "In addition, the gastric tumor with TPM3::NTRK1 (T8;N10) rearrangement also simultaneously carried the p.G12C mutation in the KRAS oncogene." (PMID 37686416, 2023).
invasive breast carcinoma (2 papers, 2015 to 2020). A carcinoma that infiltrates the breast parenchyma. "Also of interest to the outcomes of our study, according to data from The Cancer Genome Atlas (TCGA) — accessed and analyzed via the cBioPortal — NTRK1 copy number gains occur in 12% of invasive breast carcinomas (of 962 samples)." (PMID 25970776, 2015). "Overall patient survival, when considering all 825 cases of invasive breast cancers included in the PAM50 dataset, tended to be lower for cases with NTRK1 gene alterations as compared to cases with no alterations, but the statistical significance was limited (log-rank test p-value = 0.07)." (PMID 32957504, 2020).
ischemic stroke (2 papers, 2023). A stroke disorder caused by obstruction of blood flow to the brain, due to thrombotic (local blood clot formation) or embolic (due to a blood clot or other material traveling from another site) event. "Considering that the production of ROS is one of the processes present in ischemic stroke, the strong upregulation of NTRK1 in our data suggests that TrkA could have a neuroprotective role against oxidative-species-induced damage even after an average of 2.5 years from the ischemic event." (PMID 37508918, 2023).
Langerhans cell histiocytosis (2 papers, 2024 to 2025). Langerhans cell histiocytosis (LCH) is a systemic disease associated with the proliferation and accumulation (usually in granulomas) of Langerhans cells in various tissues. "Although there is a slight male predominance in JXG in general, there seems to be a more pronounced shift towards the male sex in NTRK1 fusion-positive non-Langerhans cell histiocytosis, although this needs to be verified with more future cases." (PMID 40235191, 2025). "Non-Langerhans cell histiocytosis shares a high incidence similar to that of BRAF V600E mutations, along with genetic alterations in ARAF, MAP2K1, PIK3CA, K/NRAS, and gene fusions involving BRAF, ALK, NTRK1, and ETV3-NCOA2." (PMID 38963520, 2024).
liposarcoma (2 papers, 2024 to 2026). A usually painless malignant tumor that arises from adipose tissue. "Partial responses were achieved in two cases: a liposarcoma patient with a BRCA2 mutation treated with PARP inhibitors (Olaparib and Talazoparib; PFS 29.5 months) and a patient with an NTRK1 fusion who received Larotrectinib (PFS 57.7 months)." (PMID 41562936, 2026). "These included a patient with liposarcoma harboring a BRCA2 mutation treated with PARP inhibitors (PFS 29.5 months) and a patient with an NTRK1 fusion treated with larotrectinib (PFS 57.7 months)." (PMID 41562936, 2026). "Only two cases (1 NTRK1 and 1 NTRK3) with amplification were seen in well-differentiated liposarcoma samples." (PMID 39839837, 2024).
memory impairment (2 papers, 2019 to 2020). "Since A/S/I-induced inattention, memory impairment and disorganized thinking may be due to synaptic dysfunction, we examined the effects of A/S/I on hippocampal mRNA expression of Snca α, STX1a and Ntrk1." (PMID 33088271, 2020).
mental disorder (2 papers, 2019 to 2024). A disease that has its basis in the disruption of mental process. "The role of NTRK1 in mental disorders is indirectly supported by the data that antipsychotics can reduce the level of TrkA autophosphorylation in the rat hippocampus, but the mechanism of the pro-psychotic activity of NTRK1 remains to be established." (PMID 38646100, 2024).
pleomorphic xanthoastrocytoma (2 papers, 2023 to 2026). A WHO grade ll astrocytic tumor with a relatively favorable prognosis. "In the same study, a case of PA bore a fusion of breakpoint cluster region (BCR) and NTRK2 genes (BCR-NTRK2), while a patient with pleomorphic xanthoastrocytoma (PXA) harbored the tropomyosin 3 (TPM3)-NTRK1 fusion." (PMID 41514664, 2026).
skin tumors (2 papers, 2020 to 2021). "In the 4th edition of the 2018 WHO classification of skin tumors, lesions in the spitzoid pathway (pathway 4) are characterized by mutations in HRAS, tyrosine kinase fusions (ALK, ROS1, RET, NTRK1/3, and MET), or serine-threonine kinase fusions (BRAF, MAP3K8)." (PMID 33040161, 2021).
thyroid (2 papers, 2000 to 2022). "A Canadian consensus for adult patients recommends NTRK1-3 gene fusion testing at diagnosis in unresectable or metastatic/advanced patients with all thyroid histologies and at recurrence after surgery ± RAI treatment if not already performed." (PMID 34981751, 2022). "The Canadian consensus for adult patients recommends NTRK1-3 fusion testing at diagnosis in unresectable or metastatic/advanced patients with all thyroid histologies and at recurrence after surgery ± RAI if not already performed." (PMID 34981751, 2022).
Tinnitus (2 papers, 2023 to 2024). Tinnitus is an auditory perception that can be described as the experience of sound, in the ear or in the head, in the absence of external acoustic stimulation. "It is important to note that in the tinnitus group there were also close associations of BDNF to NGFR and of NGF to NTRK1." (PMID 37736859, 2023). "In summary, BDNF and NGF interact in tinnitus with NTRK1/NGFR in a competitive, modulatory manner influencing development, degeneration, and regeneration of neuronal and non-neuronal tissue." (PMID 37736859, 2023). "In tinnitus, the predominant activity is that of other proteins, namely, the top key proteins BDNF/NTRK3/NTRK1/NTF3 in interaction with a number of Top2 key proteins, all members of the IEGs." (PMID 39062188, 2024). "BDNF and NGF, in their interaction with NTRK1/NGFR, are involved in cell growth, survival, and regeneration, with the consequence of the changes in synaptic transmission connected with tinnitus." (PMID 37736859, 2023). "The in-depth analysis of the targets of NTRK3/NTRK1/NTF3 under physiological and tinnitus conditions could help to create new starting points for therapeutic considerations." (PMID 39062188, 2024). "The key proteins of tinnitus differ from those assigned to PoS and AcouStim not only in the proteins themselves but also by the observation that the HDPs BDNF and NGF show HSIs with NGFR and NTRK1 at approximately the same level of interaction." (PMID 37736859, 2023). "The key proteins NTRK3, NTRK1, and NTF3 in tinnitus are not simply involved in activating or inhibiting processes but in remodeling of synaptic transmission processes." (PMID 39062188, 2024).
acute pancreatitis (1 paper, 2025). An acute inflammatory process that leads to necrosis of the pancreatic parenchyma. "These interactions could potentially disrupt NTRK1’s normal function, contributing to the development of acute pancreatitis (AP) by altering cellular survival and inflammatory responses in pancreatic tissues." (PMID 40385473, 2025).
adenomyosis (1 paper, 2011). The growth of endometrial tissue inside the muscular wall of the uterine corpus. "Ntrk1 levels increased as age increased in adenomyosis mice (190 ± 5 d and 240 ± 5 d, P < 0.05, compared with 90 ± 5 d)." (PMID 21385399, 2011). "Ntrk1 levels were significantly increased in adenomyosis mice compared with those in controls (190 ± 5 d and 240 ± 5 d, P < 0.05)." (PMID 21385399, 2011). "The mRNA expressions of Ntrk1 (gene of trkA) and Ngfr (gene of p75NTR) in DRG of adenomyosis and control ICR mice in the different age groups were examined by real time RT-PCR." (PMID 21385399, 2011).
adrenocortical carcinoma (1 paper, 2020). "We had a 2-year-old male patient with adrenocortical carcinoma who had three P/LP KCPG variants in NTRK1, EP300, and HMBS genes." (PMID 32371905, 2020).
alopecia (1 paper, 2022). Hair loss usually from the scalp. "For example, the CCDC41 gene variants would be present in nephronophthisis; LSS gene variants can result in alopecia; LTBP3 gene variants are characterized by hypoplastic amelogenesis imperfecta; NTRK1 gene variants have been found to cause congenital insensitivity to pain." (PMID 35911831, 2022).
atrial fibrillation (1 paper, 2018). A disorder characterized by an electrocardiographic finding of a supraventricular arrhythmia characterized by the replacement of consistent P waves by rapid oscillations or fibrillatory waves that vary in size, shape and timing and are accompanied by an irregular ventricular response. "This is corroborated by studies that identify increased NTRK1/TRKA levels associated with atrial fibrillation, and is further supported by data that revealed concomitant autocrine and paracrine regulation of NTRK1/TRKA expression by upstream NGF." (PMID 29848314, 2018).
autonomic neuropathy (1 paper, 2016). An inherited or acquired peripheral neuropathy affecting the autonomic nervous system. "Interestingly, the nerve growth factor signaling cascade (NGF/TrkA) is essential for sensory neuron survival and mutations in both NGF and its receptor, TrkA, encoded by NTRK1, lead to sensory and autonomic neuropathy." (PMID 27923065, 2016).
bipolar disorder (1 paper, 2020). A disorder of the brain that causes unusual shifts in mood, energy, activity levels and the ability to carry out day-to-day tasks. "Identification of the NTRK1 mutation linked with bipolar disorder sheds light on the new role of NGF-TrkA signaling and its relevance to mood disorders." (PMID 33235206, 2020). "They imply that the NTRK1 E492K mutation, impairs cholinergic neurotransmission, and may convey susceptibility to bipolar disorder." (PMID 33235206, 2020). "By performing whole genome sequencing analysis of a family in which bipolar disorder and ADTKD co-segregate, we identified the E492K mutation of NTRK1 that is linked with MUC1 and co-segregates with these two diseases." (PMID 33235206, 2020).
congenital mesoblastic nephroma (1 paper, 2022). A low grade childhood congenital malignant neoplasm arising from the kidney. "In tumors with a high frequency of NTRK rearrangements, such as infantile fibrosarcoma, congenital mesoblastic nephroma, and secretory breast carcinoma, NTRK1, NTRK2, and NTRK3 break-apart probes have been routinely used for the triple detection of FISH." (PMID 36612101, 2022).